CD4 (CD4 molecule)
Diseases named in the same sentence as CD4 in open-access papers (continued):
Sharing a sentence is not in itself a finding about the gene and the disease.
AIDS (continued). "In patients with a previous AIDS diagnosis (CDC stage C3), the CD4+ lymphocyte count and CD4+ percentage also increased significantly by a median of 50 cells/μL (−19 to 182.5) and 1.7% (−0.5% to 4.3%), respectively, P<0.001." (PMID 27727331, 2016). "New AIDS events were lower during HAART (5 vs 13 %; p = 0.032) and post-HAART CD4 trajectories were greater for the CS compared to NCS group." (PMID 27449671, 2016). "The advent of ART brought a dramatic reduction in AIDS-defining illnesses and mortality, benefiting HIV-infected individuals by ameliorating the rapid rate of CD4+ T cell decline and by altering molecular viral dynamics." (PMID 27478681, 2016). "Given the central importance of CD4+ T cells in containing Mtb infection, the occurrence of a progressive primary TB in HIV/AIDS patients is conceivable." (PMID 27709522, 2016). "Examples of each class of plot are given using CCASAnet data investigating trends in CD4 count and AIDS at antiretroviral therapy (ART) initiation, CD4 trajectories after ART initiation, and mortality." (PMID 26963255, 2016). "The HIV/AIDS and HIV/AIDSWC groups also showed a significant statistical difference in the CD4+ percentage between themselves (p < 0.05)." (PMID 27382604, 2016). "Median CD4 count was 386 cell/mm3 (IQR 200–586), median HIV VL was 46,504 copies/mL (IQR 11,800–151,000) and 1019 (9.9%) patients with AIDS at entry." (PMID 27603368, 2016). "However, a recent analysis has shown that risk of death or AIDS events follow a CD4+ T-cell count gradient in ART-treated participants, with clear risk for counts below 200 cells/μl but still some benefit for those individuals with a CD4+ T-cell count at least 500 cells/μl." (PMID 27427875, 2016). "The CD4 count has become the mainstay to our infectious disease colleagues to tailor the medicinal regiment of the HIV-positive and AIDS patient." (PMID 27747712, 2016). "When either of these conditions occur with a positive immunological test (CD4 count less than 350 cells/μL), it is a defining criterion for advanced HIV infection, including AIDS." (PMID 27795876, 2016). "Related factors for developing cancer among the HIV-infected population include low CD4 cell count, route of HIV contraction, co-infection with other viruses, late stage of AIDS, cigarette smoking, alcohol consumption, and advanced age." (PMID 26883427, 2016). "In this study, patients who died from non–AIDS-related diseases had been initiated on ART at higher CD4+ counts and were receiving ART for longer periods than were the matched subjects who developed AIDS." (PMID 27478681, 2016). "In untreated HIV-infected patients, the CD4/CD8 ratio can be used not only as a predictor of poor prognosis, but also as a predictor of immune restoration and AIDS-related morbidities." (PMID 27375770, 2016). "Recent studies have suggested that the CD4/CD8 ratio is a marker of T-cell activation, senescence, and activation/exhaustion in treated HIV-infected children and young adults, and that it could be independently associated with the risk of non-AIDS-related morbidity and mortality." (PMID 27490536, 2016). "Multiple linear regression analysis of factors that correlated significantly with LVSD revealed that age and CD4+ cell count were the best predictors of LVSD in our children who were HIV positive and in those with AIDS (p = 0.025 and 0.038, respectively)." (PMID 26956496, 2016). "We included people enrolled in Icona with either CD4 counts ≤350 cells/mm3 (low CD4-LC) or CD4 counts ≤200 cells/mm3 (very low CD4-VLC) and/or AIDS, starting their first PI/r-based regimen after 2008." (PMID 27348592, 2016). "Therefore, in order to reduce deaths caused by AIDS, PLHIV in Liangshan, especially those who were infected through IDU, should be timely followed up, be provided health education on adherence of treatment, and be given physical examinations, and the CD4 cell count should be monitored." (PMID 27399071, 2016).
AIDS (continued). "Children who have contracted HIV from their mothers (vertical infection) progress to acquired immunodeficiency syndrome (AIDS) more rapidly than HIV-infected adults, showing a more rapid decline in CD4+-cell counts and high plasma HIV viral load (VL)." (PMID 27490536, 2016). "A major limitation of the study were that the determination of living with HIV/AIDS was as self-report; clinical stage of HIV/AIDS while diagnosing the PTB, specific treatment against HIV/AIDS and CD4 cell count level were ignored." (PMID 28033402, 2016). "Three hundred fifty-two (89.6%) of the respondents were diagnosed for HIV before 6 months of data collection time, 269 (68.4%) of respondents had a CD4 level greater than 500, and 319 (81.2%) of them were on the first WHO stages of HIV/AIDS." (PMID 27747101, 2016). "Despite these attempts to triangulate on the magnitude of the HIV/AIDS epidemic, we assume that the CD4 progression rate, off-ART death rates, and on-ART death rates for age–sex–CD4 categories are the same throughout sub-Saharan Africa." (PMID 27733281, 2016). "The groups HIV/AIDS and HIV/AIDSWC showed a decrease of the CD4+ percentage when compared with the healthy group (p < 0.0001)." (PMID 27382604, 2016). "A large proportion of individuals infected with HIV-2 remain aviremic for years, but it is not clear whether these individuals have CD4+ T cells with markers of elevated activation and other pathological characteristics, thereby increasing their risk of AIDS and non-AIDS-related illnesses." (PMID 27525551, 2016). "In the macaque model of AIDS, physical contact between CD8+ and CD4+ cells appears to be the most important aspect for mediating CNAR and viral inhibition, which depends upon the origin of both, CD8+ and CD4+ cells." (PMID 26551355, 2015). "404/548 patients had available data about AIDS at HIV diagnosis, of these 34% were AIDS presenters, and 49.3% had CD4 count ≤350/mm3." (PMID 26543523, 2015). "While CD4 and clinical staging are a routine component of HIV services in Yunnan, these data are reported in detail to the National AIDS Treatment Information Management System, but are incomplete in the National PMTCT Information Management System." (PMID 26407096, 2015). "Data analysis showed a significant correlation between acceptance of ART, CD4 levels and the QOL of all domains (P<0.05), which was consistent with the results of Tsevat J’s study: the symptoms of AIDS patients always occurred together with their bad QOL." (PMID 26308088, 2015). "Timely initiation of ART (before profound CD4+ T-cell depletion occurs) could at least in part prevent irreversible immune dysfunction, and reducing persistent immune activation might possibly limit the occurrence of non-AIDS clinical events in HIV-infected people." (PMID 25671649, 2015). "In contrast to thymic-derived CD4+CD25+FOXP3+ Tregs, their origin and their role in the pathophysiology of autoimmune diseases (AIDs) are less understood." (PMID 25926835, 2015). "Our study will test this assumption and contribute to the knowledge gap in developing countries, where CD4 count is the immunological marker most used for determining ART initiation and HIV/AIDS disease monitoring." (PMID 26370702, 2015). "A 6-month cohort study of 34 outpatients with HIV/AIDS tested the granule’s effects on regulation of immune activation molecules CD38 and human leukocyte antigen-D related to CD4 + T and CD8 + T cells." (PMID 26699285, 2015). "We demonstrate that irrespective of ART use, patients with pancytopenia, have a lower CD4 cell count, lower BMI, higher HIV viral load and higher clinical AIDS prevalence (p < 0.05)." (PMID 26703689, 2015). "The method uses the concept that a predictable level of occurrence of AIDS or other HIV-related clinical symptoms which lead to presentation for care, and hence diagnosis of HIV, arises in undiagnosed people with a given CD4 count." (PMID 25768925, 2015).
AIDS (continued). "These two indexes have also been adopted in TCM treatment of AIDS, and a few studies have demonstrated that TCM is very promising in reducing HIV viral loads, increasing CD4 + T cell counts, or affecting other immunological indicators." (PMID 26699285, 2015). "Risk factors for death were assessed using Cox regression models stratified by site and adjusted for sex, baseline age, nadir pre-ART CD4 count, calendar year of ART initiation, clinical AIDS at baseline and type of ART regimen." (PMID 26165322, 2015). "Indeed, more than 75% of AIDS associated cryptococcosis cases develop in the late-stage of HIV infection when the CD4+ T-lymphocyte count falls below 50 cells/μl, and in experimental animal models CD4 T cell deficiency results in defective control of C. neoformans infection." (PMID 26252005, 2015). "It was the same HIV-infected subject, with a low CD4 count and CD4/CD8 ratio comparable to some of the AIDS patients that clustered with the AIDS patients in the FLOCK analyses." (PMID 26402620, 2015). "The repression of CD4+ T cells and impairment of macrophages’ activity in HIV/AIDS results in down-regulation of the body’s immune response to infections, such as MTB." (PMID 26779470, 2015). "Thirty-six patients (44%) were at AIDS stage, HIV viral load was inferior to 20 copies/ml in 59 patients (74%), and CD4 cell count was inferior to 200/mm3 in 12 patients (15%)." (PMID 26571117, 2015). "The PIMA POC CD4 analyzer could allow patients to receive their CD4 results earlier and immediately begin treatment, thereby reducing one of the largest causes of HIV-related mortality, particularly in those areas were a high proportion of people are diagnosed very late stages of AIDS." (PMID 25905775, 2015). "For example, AIDS diagnosis was originally modelled as the end-point for disease but this has subsequently been refined to incorporate both AIDS and HIV diagnoses as well as a number of other intermediate disease states based on CD4 count." (PMID 26490744, 2015). "Among individuals with CD4 count ≤ 350 cells/mm3 or missing CD4 but diagnosed with AIDS, 12.9% of patients were lost to follow-up between HIV diagnosis and CD4 testing, a further 11.4% were lost before ART initiation, and 31.4% died." (PMID 26348214, 2015). "In this study, the negative effect of older age on early mortality was clear overall, after adjusting by CD4 cell count, HIV transmission group, or other factors, or when stratifying by time elapsed from first HIV-positive test to AIDS." (PMID 26067992, 2015). "Immunological markers (CD4 count) are used in developing countries to decide on initiation of antiretroviral therapy and monitor HIV/AIDS disease progression." (PMID 26370702, 2015). "HIV infection in ART-naive individuals is typically characterized by a decline in CD4+T cell count and a rise in plasma HIV RNA (viral load), which eventually leads to opportunistic infections, development of AIDS and AIDS-related deaths if left untreated." (PMID 26121491, 2015). "Based on the natural history of the CD4 count of people living with HIV and AIDS (PLWHA), we constructed a dynamic compartmental model of HIV transmission among Chinese MSM to project the number of HIV new infections and prevalence over 10 years." (PMID 26039075, 2015). "Statistically significant differences (p < 0.05) were found in the following variables: employment status, BMI, CD4 cell count, HIV viral load, clinical AIDS and ART use." (PMID 26703689, 2015). "Patients with pancytopenia had lower BMI and lower CD4 count, as well as higher HIV viral load and higher proportions of unemployment, clinical AIDS and antiretroviral treatment (ART) use (p < 0.05)." (PMID 26703689, 2015). "Disease progression was defined as a fall in the CD4 count to <350 cells/microL on 2 consecutive tests, the start of anti-HIV therapy, or the onset of AIDS-indicator diseases." (PMID 26000028, 2015).
AIDS (continued). "CD4 + T cell counts and HIV loads are gold standard evaluation criteria for AIDS therapy as recommended by the World Health Organization (WHO)." (PMID 26699285, 2015). "Similar trends were seen at GHESKIO-Haiti (median CD4=164, 142 and 83 cells/μL for alive, LTFU and dead, respectively; proportion with AIDS=20, 24 and 44%, respectively)." (PMID 26165322, 2015). "The HIV-1 primarily replicates within CD4+ T lymphocytes but can also infect myeloid cells, including macrophages and dendritic cells leading to the acquired immunodeficiency syndrome (HIV/AIDS)." (PMID 26390290, 2015). "CD4/CD8 ratio is considered a marker of immunosenescence, but its role as a predictor of non-AIDS event is still controversial." (PMID 26355305, 2015). "More recently, it became clear that the fight against HIV/AIDS requires point-of-care (POC) technologies for rapid, reliable and affordable CD4+ analysis, to be used especially in rural areas." (PMID 25622041, 2015). "Another study demonstrated marginal protection against disease progression and death among women despite higher average CD4 counts at the time of seroconversion for HIV, progression to AIDS, and death for female patients." (PMID 26107253, 2015). "Mortality in the early ART treatment period is higher among patients with low BMI, low CD4+ T-cell counts, low hemoglobin, low serum albumin and phosphate levels, advanced HIV/AIDS stage, and immune reconstitution inflammatory syndrome." (PMID 26161268, 2015). "Markers of HIV disease severity were independently predictive of AIDS death, including last pre-HAART CD4+ count below 200 cells/mm3, prior ADI, and both last pre-HAART log10 HIV RNA viral load r and peak log10 HIV RNA viral load." (PMID 26699870, 2015). "Previous studies and reports in Sub-Saharan Africa showed that 35–65 % of HIV patients initially present with a CD4 cell counts less than 200 cells/μl or with an AIDS-defining illness and 20–40 % start ART with a CD4 counts <100 cells/μl." (PMID 26633988, 2015). "The median age at ART initiation was 36 years (IQR: 30–44), subjects were predominantly male (63%), median CD4 count was 156 cells/μL (IQR: 60–251) and 26% of subjects had clinical AIDS prior to starting ART." (PMID 26165322, 2015). "Characteristics of patients were as follows: median age 42.2 years (19.1–79.1), hepatitis B virus (HBV) and/or hepatitis C virus (HCV) co-infection 47 (18.8%), median CD4 610 (2–1758), CD8 793 (113–4010), presence of a past AIDS event for 88 patients (23%)." (PMID 25394153, 2014). "In fact, anemia has been associated with an increased risk of death in HIV-infected patients, independently of many indicators of poor prognosis, such as: low CD4 cell count, high HIV viral load or the manifestation of AIDS-defining conditions." (PMID 25005803, 2014). "However, CD4+ T-cell deficiency persists in up to 40% of patients receiving ART, particularly those patients who commenced ART with a very low CD4+ T-cell count, and is associated with persistent immune activation and an increased risk of ‘serious non-AIDS events'." (PMID 25505958, 2014). "The finding that anemia is more prevalent in older patients and those with lower BMI, lower CD4 cell count, higher HIV viral load and clinical AIDS has been previously documented." (PMID 25005803, 2014). "Again, patients starting a third line regimen were highly immunocompromised at HAART initiation, with a median CD4 of 63 cells/mm3 (IQR 26 to 130) and 26 (63%) having had prior AIDS." (PMID 25221931, 2014). "The CD4/CD8 ratio was lower in cases (0.44 vs. 0.70, P<0.0001), with higher discriminatory ability for the detection of non-AIDS events than the CD4 count, CD8 count and nadir CD4." (PMID 24497929, 2014). "By controlling for time-dependent covariates including CD4 counts and HIV-1 RNA concentration, it was found that HAART substantially reduced the rate of progression to AIDS or deaths by 86%." (PMID 25243780, 2014).
AIDS (continued). "For every 100 cells per mL increase in CD4 at diagnosis, PLHIV were 0.57 times less likely to develop AIDS (95% CI 0.53–0.61)." (PMID 25095830, 2014). "In our research, most AIDS patients (84.2%) were in stage III or IV, and accepted ART when their CD4+ cells counts were <200 cells/μL." (PMID 25360785, 2014). "At cART initiation, the median age was 38.6 years (IQR: 32.2–46.0), 9734 (64.8%) were men, median CD4 cell count was 239 (IQR: 130–336) and 2668 (17.8%) had a prior AIDS event." (PMID 25393990, 2014). "Often, HIV-infected patients with EPTB present with advanced immune suppression with CD4 counts <200 cells/μl, and hence their classification as a WHO Stage 4 AIDS defining disease." (PMID 24755603, 2014). "The prevalence of anemia differed significantly (p < 0.05) by: age, education level, employment status, BMI, CD4 cell count, HIV viral load, platelets count, white blood cell count, clinical AIDS and antiretroviral treatment use." (PMID 25005803, 2014). "Among patients with AIDS, PCP was the first manifestation of AIDS for 105 (44.8%); only 4 (5.0%) had CD4 lymphocyte counts >200 cells/mm3." (PMID 25148074, 2014). "CD4 cell count, initial viral load, calendar year of commencing ART and age are more important determinants of AIDS and mortality than injecting status for in-treatment PLHIV in Victoria, Australia." (PMID 25523753, 2014). "In univariate analyses, poorer survival after NADC diagnosis was associated with intravenous drug use (IVDU) mode of infection, lower CD4+ T-cell count at NADC diagnosis and previous AIDS event." (PMID 24760049, 2014). "For example, studies using the same CD4 threshold of 350 cells/mm3 to define LP found between 45% and 48% of MSM presented late to HIV/AIDS services." (PMID 25535408, 2014). "Participants with AIDS had significant lower QOL in the level of independence domain (p = 0.018) and those with CD4 count ≥ 350 cells /mm3 had better QOL scores in the physical, psychological and level of independence domains." (PMID 25426192, 2014). "Poisson regression models were used to compare incidence between the two groups, after adjustment for potential confounders (age, transmission group, origin, AIDS, PCP prophylaxis, viral load, CD4, nb of previous ARV)." (PMID 25397525, 2014). "The increases in CD4 monitoring of both new HIV cases and previously diagnosed cases were facilitated by structural expansions of the national AIDS programs and increases in the availability of testing materials/equipment." (PMID 24901790, 2014). "Six children had been diagnosed with AIDS stage III–IV and the other twenty children had moderate-to-severe immunosuppression and a CD4 T cell percentage <15-20%." (PMID 24994004, 2014). "Botswana's AIDS response included free antiretroviral treatment (ART) since 2002, achieving 80% coverage of persons with CD4<350 cells/μl by 2009–10." (PMID 25003870, 2014). "Most HIV-infected patients exhibit a gradual decline in CD4 cells throughout the course of their infection; the rate of disease progression from asymptomatic HIV infection to AIDS varies between patients." (PMID 25495598, 2014). "When restricting the dataset to those with 10 years of follow-up, definitions A, E and F and J demonstrated the lowest hazard of AIDS, Death, ART or CD4<350 cells/mm3 compared to definitions with single measurements or higher levels of viremia." (PMID 24489776, 2014). "Egger (2007) indicated that there are several predictors of mortality for HIV/AIDS patients who are undergoing treatment on ART, including CD4 count, viral load, total lymphocytes, body mass index and adherence." (PMID 25279328, 2014). "Their most recent CD4 counts ranged from 0 to 1200 with a mean CD4 count of 407; 62.7% (n = 470) reported that they had other comorbid medical conditions in addition to HIV/AIDS." (PMID 24800065, 2014).